VEGFA (vascular endothelial growth factor A)
Diseases named in the same sentence as VEGFA in open-access papers (continued):
Sharing a sentence is not in itself a finding about the gene and the disease.
diabetes (continued). "Our research results showed that 28 ginsenosides in ginseng might be against diabetes mellitus by modulating related proteins such as VEGFA, Caspase 3, and TNF-α." (PMID 36646777, 2023). "Therefore, interventions that suppress VEGFA-VEGFR2 signaling delay the onset of early kidney disease in patients with diabetes." (PMID 38075072, 2023). "Diabetes-induced cMAP4K2 up-regulation could act as an endogenous miRNA sponge for miR-377, inducing increased VEGFA expression." (PMID 35963645, 2022). "As for the molecular mechanism of anti-diabetes, five compounds with better activity in vitro were selected to explore their effects on the AKT1, IL-6 and VEGFA mRNA expression, indicating that their anti-diabetes mechanism was related to PI3K-AKT signaling pathway." (PMID 36559019, 2022). "Upregulation of VEGFA in diabetic kidneys protects the microvasculature from injury and that reduction of VEGFA in diabetes may be harmful." (PMID 35885938, 2022). "This SNP, which is located in the promoter region of the VEGFA gene in a region marked by H3K27Ac and H3K4me3, has a high possibility of being a transcription factor binding site and has been extensively studied in the context of diabetes mellitus." (PMID 33800431, 2021). "Finally, some links between DN and DR/DNp were found with NOS3, and VEGFA, mainly due to the number of factors and genes interactions that complement each other leading to diabetes disease progression." (PMID 35069435, 2021). "There have been studies assessing the expression of LIF and VEGFA as implantation modulators; however, the expression changes of these molecules in diabetic conditions and the effects of diabetes treatment drugs on the endometrial expression of these molecules have not been well-understood." (PMID 33062917, 2020). "Furthermore, we carried out a Multivariate ANOVA in order to unveil the effects of fixed factors (independent variables) on dependent variables (diabetes duration, glycated hemoglobin HbA1c, TGFβ1, VEGFA, PlGF)." (PMID 33334029, 2020). "We analyzed whether obesity and diabetes affected molecules involved in angiogenesis; such as TF, VEGFA and two miRNAs (miR-126 and miR145)." (PMID 33022994, 2020). "rHDL is known to rescue diabetes-impaired expression of VEGFA, and this may also lead to the support of increased glycolytic flux in hypoxia and underpin some of the known pro-angiogenic activity of rHDL." (PMID 32455604, 2020). "Aberrant expression of both LIF and VEGFA has been previously reported in the context of diabetes." (PMID 33062917, 2020). "In our study, consistent with previously published data, VEGFA expression was significantly increased in the glomerulus of diabetic Hif1α+/− compared to the diabetic Wt, indicating a faster progression of renal dysfunction in diabetes." (PMID 28774305, 2017). "Therefore, a regression analysis was firstly conducted to confirm that SNPs of VEGFA or VEGFR2 were still associated with the risk of CHD when the effects of smoking, alcoholic consumption, diabetes, or hypertension were excluded." (PMID 27175642, 2016). "In view of increased vascular endothelial growth factor-A (VEGF-A) expression and renal dysfunction in early diabetes, we designed a study to test whether VEGF-A inhibition can prevent early renal injury and dysfunction." (PMID 24759991, 2014). "Moreover, the product of VEGFA interacts with resveratrol, which has been shown to have a beneficial influence in some metabolic traits, including diabetes." (PMID 22479202, 2012). "Another intriguing example is HDAC4, which may deacetylate hypoxia inducible factor 1 subunit alpha (HIF‐1α) that upregulates vascular endothelial growth factor A (VEGFA), which consequently leads to suppression in osteogenic precursor cells differentiation and aggravate diabetic OP in mice." (PMID 40170748, 2025).
diabetes (continued). "Thus, we proposed that AURKA might stimulate microvascular endothelial cells to form a vascular network via two distinct mechanisms: induction of VEGFA expression in diabetes-related limb ischemia and increased sensitivity of endothelial cells to VEGFA." (PMID 36977984, 2023). "In short-term diabetes (3 weeks), suramin, a drug used clinically, affects renal function and the expression of vascular endothelial growth factor A (VEGF-A), which may be involved in the pathogenesis of diabetic nephropathy, the main cause of end-stage renal disease." (PMID 37834118, 2023). "If this interpretation is correct, it seems tempting to imply miR-1281 as a novel pathogenetic marker of retinal microangiopathic damage in patients with diabetes, which may explain, at least in part, how chronic sustained hyperglycemia could abnormally up-regulate VEGFA in retinal cells." (PMID 32849308, 2020). "It has been found that vascular endothelial growth factor A (VEGFA) and transforming growth factor beta receptor 1 (TGFBR1) are upregulated in diabetes." (PMID 40166052, 2025). "Diabetic Peripheral Neuropathy (DPN), a debilitating complication of type 2 diabetes mellitus (T2DM), stems from bioenergetic failure and reduced vascular endothelial growth factor-A expression (VEGF-A), persisting despite optimal glycemic control." (PMID 40933195, 2025). "The expressions of IL17A, MMP2, IL10 and IL6 are up-regulated with diabetes that promote the progression of OP, whereas the expressions of FGF2 and VEGFA are down-regulated." (PMID 38250601, 2024). "Consequently, a refined selection comprising seven genes (MMP2, MMP9, IL17A, IL10, FGF2, IL6 and VEGFA) and eleven pharmacological agents has emerged, exhibiting promise in delivering therapeutic effects aimed at mitigating the occurrence of OP in individuals afflicted with diabetes." (PMID 38250601, 2024). "With the objective of investigating new biomarkers for the early detection of diabetes complications, such as DN, and their expression profiles during aging, we analyzed the expression levels of the TNFR1, VEGFA, CD147 and MCT1 markers." (PMID 37863950, 2023). "After RT-qPCR analysis, it was found that the mRNA expression of VEGFA, KDR, MAPK14, and PPARA showed significant differences between normal and diabetes mellitus mice, with a retracement after FBT treatment." (PMID 38304230, 2023). "AKT1, VEGFA and IL-6, as enriched targets or downstream key factors of the PI3K-AKT pathway, are relevant factors in the pathogenesis of diabetes." (PMID 36559019, 2022). "We identified 8 hub genes (JUN, ATF3, VEGFA, SLC2A1, HK2, PTGS2, PFKFB3, and KLF6) that were enriched in response to hypoxia, angiogenesis, vasculogenesis, hypoxia-induced signaling, cancer, diabetes, and transplant-related disease pathways." (PMID 36482897, 2022). "However, VEGFA knock out diabetic mice has adverse consequences characterized by global sclerosis and death which illustrate the opinion that the upregulation of VEGFA in diabetic kidneys may protect the microvasculature from injury and reduction of VEGFA in diabetes may be harmful." (PMID 35637650, 2022). "Our two hub genes, JUN and VEGFA, showed enrichment in the AGE-RAGE signaling pathway in diabetes complications." (PMID 36482897, 2022). "For example, the coding genes VEGFA, HGF1R, and BCL2 have been found to be involved in diabetes and DR progression." (PMID 34707685, 2021). "GCG, IRS1, VEGFA, STAT3, CCL2, CASP3, and APOE as diabetes mellitus-related proteins and SREBF1, LPL, PPARA, APOB, GPT, MAPK8, and FASN as NAFLD-specific proteins were identified as possible discriminating factors between the two studied diseases." (PMID 35154608, 2021).
diabetes (continued). "For example, the coding genes VEGFA, HGF1R, and BCL2, which exhibiting higher degree and BC in the network, have been found to be involved in diabetes and DR progression." (PMID 34707685, 2021). "Meanwhile, compared with the diabetes + hUSCs‐Exo control group, the expression of VEGFA, MCP‐1, TGF‐β1 and TNF‐α was reduced in the diabetes + hUSCs‐Exo miR‐16‐5p group (all P < .05), while elevated levels were detected in the diabetes group (all P < .05)." (PMID 31568645, 2021). "The expression of VEGFA, MCP‐1, TGF‐β1 and TNF‐α was increased in the diabetes, diabetes + hUSCs‐Exo control and diabetes + hUSCs‐Exo miR‐16‐5p groups compared with the normal group (all P < .05)." (PMID 31568645, 2021). "Subsequently, decreased VEGFA production and signaling via VEGFR2 play a central role to reduce blood flow reperfusion in diabetes." (PMID 34483928, 2021). "There is much evidence supporting the concept that HDL augments diabetes-impaired HIF-1α activity and VEGFA expression, resulting in the rescue of angiogenesis both in vitro and in vivo." (PMID 32455604, 2020). "We recently discovered that rHDL rescues diabetes-impaired angiogenesis through its ability to increase HIF-1α stability and VEGFA production." (PMID 30206364, 2018). "Therefore, the association between 6 VEGFA/VEGFR2 genetic polymorphisms and the risk of CHD in a Chinese Han population was clarified by our study which also adjusted for several confounding factors including smoking status, alcohol consumption, hypertension and diabetes." (PMID 27175642, 2016). "Inhibition of VEGFA and fibronectin expression in the kidney by DHI can reduce mesangial expansion and accumulation of AGEs or other macromolecules, and ameliorate diabetes-induced proteinuria." (PMID 26061387, 2015). "However, in diabetes, local VEGFA expression becomes dysregulated, as rodent models of diabetic nephropathy show elevated renal VEGFA, and pharmacological blockade of VEGF signaling in these models reduces albuminuria and glomerular injury." (PMID 41300838, 2025). "However, overexpression of circ‐IGF1R increased HK2 and VEGFA expression, and HEV treatment ulcerated tissue in mice with diabetes." (PMID 38984951, 2024). "Prominent genes were RHOA, AKT1, RAC1, MDM2, CDKN1A, and VEGFA, which play important roles in TGF-beta and mTOR signaling (KEGG database), signaling by Wnt and by NOTCH (Reactome database), and in complications in diabetes mellitus (DisGeNET database)." (PMID 35742976, 2022). "Our results uncovered that AS-IV can protect retinal cells against diabetes induced retinopathy, which may act on target proteins AKT1, CASP3 and HIF1α, VEGFA, IL6, IL1β, SRC and CTNNB1, and might be involved in the regulation of PI3K-AKT signaling pathway." (PMID 35814228, 2022). "Besides the targeting of VEGFA/VEGFR1, vandetanib’s target EGFR can also potentially help diabetes pathology." (PMID 32764756, 2020). "Similarly, genes ESR1, SERPINE1 and VEGFA are shared across diabetes (EGFR, GSTP1, SERPINE1, ESR1, VEGFA and EGF) and obesity (CCND1, SERPINE1, ESR1 and VEGFA), which is in line with previous reports that obesity is a risk factor of diabetes." (PMID 31835887, 2019). "VEGFA was not affected by diabetes, whereas VEGFB was significantly downregulated (p < 0.001 vs the control group)." (PMID 31001672, 2019). "In this study, in the animal model of overexpressed miR-15a, acid sphingomyelinase and VEGFA levels were directly reduced to nondiabetic levels; diabetes-induced increased retinal permeability was also prevented in these mice." (PMID 30980286, 2019). "In the animal model of overexpressed miR-15a, ASM and VEGFA levels are directly reduced to nondiabetic levels; diabetes-induced increased retinal permeability is also prevented in these mice." (PMID 29074557, 2017).
diabetes (continued). "Therefore, the expression of ARHGEF26 in glomerular endothelial cells may facilitate VEGFA-induced VEGFR-2 internalization on the cell surface via macropinocytosis, thereby protecting the glomerular microvasculature in diabetes." (PMID 40690456, 2025). "In cancer and diabetes, AURKA has been demonstrated to function in glucose metabolism, suggesting that AURKA might promote the high glucose metabolism in microvascular endothelial cells to relieve VEGFA resistance." (PMID 36977984, 2023). "The role of hsa-miR-503 in pathomechanism of diabetes complications depends on mitochondrial activity (DHFR), cell cycle control (CCNE2), cell protection (SOD2), podocyte migration (ANLN), inflammatory process (IL10, EFE2, VEGFA) and fibrosis (COL1A1), showing its contribution to CKD development." (PMID 36859746, 2023). "Moreover, the recovery of brain vascular alterations has been found in animal models, including diabetes, suggesting that the crosstalk between NGF and VEGFA might participate in retinal cell survival." (PMID 36291113, 2022). "Moreover, diabetic rats showed a decrease in eNOS and VEGFa protein expression, compared to rats without diabetes." (PMID 34545676, 2021). "However, endometrial LIF and VEGFA expressions modulation during implantation in the context of diabetes is not well-understood." (PMID 33062917, 2020). "COMF and its active components quercetin, kaempferol, isorhamnetin, luteolin and apigenin could regulate AKT1, VEGFA and IL-6 mRNA levels and improve the dysregulation of PI3K-AKT pathway signaling to intervene the inflammation and trauma manifested during the development of diabetes." (PMID 36559019, 2022). "GCG, IRS1, VEGFA, STAT3, CCL2, CASP3, and APOE are the 7 DEPs that are related to diabetes mellitus as specific proteins but not seen among the central proteins of fatty liver disease." (PMID 35154608, 2021). "Diabetes induced an increase in immunoreactive ANGPT2 (p < 0.05) but did not alter ANGPT1, VEGFA, VEGFB, IGFBP2 or SEMA6A." (PMID 31001672, 2019).
glioma (939 papers, 2000 to 2026). A benign or malignant brain and spinal cord tumor that arises from glial cells (astrocytes, oligodendrocytes, ependymal cells). "The effect of Trp deficiency on the GCN2 pathway and VEGFA expression was then investigated in glioma cell lines GL261, U87MG, U251, and A172." (PMID 39065567, 2024). "FGL2, IL10, TGFB1, and VEGFA were secreted immunosuppressive molecules in glioma and were consistently upregulated in high-risk group from all four datasets." (PMID 37864127, 2023). "This is consistent with the Pearson correlation analysis, which showed that the expression of SOCS3 and VEGFA has a strong positive association (R-value = 0.69, p < 2.2 × 10−16) in glioma." (PMID 33804433, 2021). "In agreement with our earlier observations, B7H3 and VEGFA were significantly decreased in IDH1-mutated gliomas compared to that in IDH1-WT glioma samples." (PMID 34079802, 2021). "B7H3 and VEGFA are decreased in IDH-mutated gliomas and these two proteins are further reduced when D-2-HG accumulates highly in IDH-mutated gliomas." (PMID 34079802, 2021). "Meanwhile, the downregulation of VEGFA in IDH-mutated gliomas is also associated with low protein level of B7H3 and high 2-HG level." (PMID 34079802, 2021). "Our bioinformatics analysis, immunoblotting, and IHC staining reveal that B7H3 is positively associated with VEGFA in gliomas." (PMID 34079802, 2021). "Second, significant publication bias was observed in the analysis of glioma risk and VEGFA rs3025039 in the recessive model." (PMID 29137376, 2017). "In the present study, we assessed the contribution of 8 VEGFA SNPs to the risk of glioma and observed several positive associations at 6 SNPs." (PMID 29137376, 2017). "To increase statistical power, we conducted a systematic review and meta-analysis of published studies investigating the associations between VEGFA polymorphisms and glioma susceptibility." (PMID 29137376, 2017). "In the current study, a meta-analysis was performed to derive a more precise estimation of the involvement of VEGFA polymorphisms in glioma development." (PMID 29137376, 2017). "Five of these studies were excluded, including two that did not investigate the polymorphism of interest, one that did not provide exact genotypes, and two that investigated the association between VEGFA polymorphisms and the prognosis of glioma." (PMID 29137376, 2017). "Subsequent studies with larger sample sizes using different ethnicities are needed to evaluate the association between VEGFA gene polymorphisms and various types of glioma." (PMID 29137376, 2017). "A sufficient number of cases and controls were pooled from different studies and a more accurate estimation of the associations between VEGFA SNPs and glioma risk compared to individual studies was evaluated." (PMID 29137376, 2017). "Notably, combined high expression of XBP1 and VEGFA was significantly associated with poor glioma prognosis." (PMID 40621799, 2025). "VEGFA/VEGFR1 is one of the most important ligand-receptor pairs associated with recruitment of monocytes/macrophages to form GAMs in a specific TME regions around glioma." (PMID 37790751, 2023). "A study that evaluated the association of VEGF and KDR SNPs in patients with severe gliomas showed that VEGFA-2578 C/A and VEGFA-1154G/A increased the risk of severe glioma and that the “CAGT” haplotype of the KDR gene altered the aggressiveness of high-grade glioma and the risk of grade IV tumors." (PMID 36559251, 2022). "B7H3 and VEGFA were both downregulated in IDH-mutated glioma cells and tissue specimens." (PMID 34079802, 2021). "Therefore, larger, preferably population-based case-control studies, as well as mechanistic studies involving variants of VEGFA on glioma progression, are warranted to validate our findings and to further investigate their roles in the development of glioma." (PMID 29137376, 2017).